CDK4 (cyclin dependent kinase 4)
Diseases named in the same sentence as CDK4 in open-access papers (continued):
Sharing a sentence is not in itself a finding about the gene and the disease.
breast cancer (continued). "Recent single-cell profiling of HR+/HER2− metastatic breast cancer treated with cyclin-dependent kinase 4/6 (CDK4/6; encoded by CDK4 and CDK6) inhibitors has revealed distinct TIME patterns correlated with therapeutic response within the framework of targeted therapy." (PMID 41550427, 2025). "Therefore, the data collectively discovered an NSRP1/NSD2/IFN axis implicated in CDK4/6i resistance in ER+ breast cancer cells." (PMID 39667501, 2025). "In the PALOMA 3 trial, 4.7% of patients developed on-treatment RB1 mutations, indicating that CDK4/6 inhibitor therapy may provide selective pressure, leading to the development of Rb loss in a subset of breast cancer patients." (PMID 40075623, 2025). "In this study, we demonstrated significantly elevated levels of XBP1 and XBP1s in HR+/HER2− breast cancer, which were associated with an unfavorable therapeutic response and poor prognosis in patients who received the combination treatment of CDK4/6 inhibitors plus endocrine therapy." (PMID 40940685, 2025). "Finally, we find evidence of novel CDK6 mutations in breast cancer patients and concordance between experimental and clinical correlates of response to CDK4/6 inhibitors." (PMID 41279360, 2025). "Furthermore, CDK4/6 inhibitors (CDK4/6i) are reported to be applicable as adjuvant therapy in patients with high-risk early-stage breast cancer." (PMID 40142360, 2025). "CDK6 overexpression has been linked to reduced sensitivity to CDK4/6is in breast cancer." (PMID 40244377, 2025). "The aim of our study was to evaluate the efficacy of CDK4/6i plus a change in endocrine therapy, after progression on initial CDK4/6i + endocrine therapy in patients of ER+ HER2- advanced breast cancer and to identify patient characteristics associated with differential benefits." (PMID 40427107, 2025). "Finally, we provide evidence of novel CDK6 mutations in breast cancer patients and concordance between experimental and clinical correlates of response to CDK4/6 inhibitors." (PMID 41279360, 2025). "The postMONARCH study, a phase 3, randomized, placebo-controlled trial, demonstrated that switching to abemaciclib plus fulvestrant significantly reduced the risk of disease progression in HR+, HER2− advanced breast cancer with progression on prior CDK4/6i plus endocrine therapy." (PMID 40141282, 2025). "Furthermore, in ER+/HER2− breast cancer following progression on CDK4/6i, genetic alterations associated with KAT6A inhibition were found to be enriched in cell cycle and associated pathways, such as the E2F pathway." (PMID 41357671, 2025). "Similarly, in the CORALLEEN trial, the combination of another CDK4/6 inhibitor (Ribociclib) with letrozole was found to be more effective than chemotherapy in downstaging high-risk luminal B breast cancer." (PMID 40104496, 2025). "Finally, we demonstrated that low expression of MAP2K7 and pJNKT183/Y185 was associated with poor outcomes in early and metastatic ER+ breast cancer patients treated with endocrine therapy and CDK4/6 inhibition." (PMID 40826108, 2025). "Moreover, endocrine therapy combined with cyclin-dependent kinase 4/6 (CDK4/6) inhibitors is now a standard of care in high-risk early breast cancer." (PMID 41561045, 2025). "Notably, no prior studies have specifically investigated ILD associated with combined CDK4/6i and radiotherapy in breast cancer patients." (PMID 41244784, 2025). "AURKA amplification has also been implicated in resistance to CDK4/6i in ER+/HER2− breast cancer." (PMID 40949156, 2025). "Furthermore, CDK4 overexpression was associated with poor outcomes in ER+/HER2− early breast cancers." (PMID 40244377, 2025). "Given that canonical and non-canonical TGFβ pathways affect chromatin accessibility and that CDK4/6 inhibition induces chromatin remodelling by enhancer activation in breast cancer, SMAD2 splice variants and corresponding phospho-isoforms are critical modulators of gene transcription in NSCLC." (PMID 40319202, 2025).
breast cancer (continued). "Additionally, impairing mutations or loss of the RB1 gene have been reported in breast cancer patients with poor responses to CDK4/6is." (PMID 40244377, 2025). "Notably, CDK4 overexpression is frequently implicated in breast carcinoma progression, and pharmacological inhibition of CDK4/6 has demonstrated clinical efficacy in suppressing tumor proliferation." (PMID 40864776, 2025). "We next sought to determine whether specific biological processes linked to CDK4/6i–induced senescence in luminal breast cancer might be also regulated by enhancers activated during INX-315–induced senescence." (PMID 38047585, 2024). "However, with the recent approval of cyclin-dependent kinase 4/6 (CDK4/6) inhibitor abemaciclib for the treatment of high-risk early-stage breast cancer, the therapeutic landscape is changing." (PMID 39461262, 2024). "Therefore, the phase II BYLieve trial evaluated patients with PIK3CA-mutated, HR-positive, HER2-negative advanced breast cancer after progression on a CDK4/6 inhibitor plus an AI and alpelisib continued to show efficacy in combination with fulvestrant." (PMID 38396649, 2024). "Furthermore, two studies (NeoPAL27 and CORALLEEN28) demonstrated comparable efficacy and superior safety of neoadjuvant CDK4/6 inhibitors + ET for high-risk luminal breast cancer compared to conventional neoadjuvant chemotherapy regimens." (PMID 38448600, 2024). "It has been demonstrated that susceptibility to palbociclib treatment in breast cancer may be predicted by immunohistochemical identification of Thr172-phosphorylated CDK4 (an activating phosphorylation performed through the CDK-activating kinase, CAK)." (PMID 38983782, 2024). "To assess whether our 3D system recapitulate the resistance of breast cancer cells to CDK4/6 inhibitors and endocrine therapy, which is associated with low FAT1 levels and Hippo pathway activation, we conducted a comparative analysis of gene expression data." (PMID 38565950, 2024). "Targeting transcription-associated CDK9 synergizes with CDK4/6 inhibitor to drive tumor regression in multiple models of endocrine- and palbociclib-resistant ER+ breast cancer, which could address the challenge of overcoming resistance in patients." (PMID 37801608, 2024). "The ELAINE 1 study explored whether lasofoxifene has better antitumor activity than fulvestrant in advanced breast cancer patients with ESR1 mutation after progression on CDK4/6 inhibitors combined with AI therapy." (PMID 38090370, 2023). "Therefore, the development of a PEG10 inhibitor is a rational approach for the treatment of breast cancer with PEG10-associated resistance to CDK4/6 inhibitor." (PMID 38017459, 2023). "We examined the expression of the four predominant cell cycle cyclins and CDKs to establish if inhibition of CDK4/6 by palbociclib was associated with alteration of CDKs or cyclins that have been implicated in acquisition of resistance to palbociclib in luminal breast cancer." (PMID 37298855, 2023). "Recently, the CDK4/6i abemaciclib was approved as adjuvant therapy for high-risk ER+ breast cancer." (PMID 37502925, 2023). "Amcenestrant (SAR439859) is a nonsteroidal, orally bioavailable, SERD studied in clinical trials (AMEERA) in postmenopausal women with HR+/HER2− advanced breast cancer and in association with CDK4/6 inhibitors, such as palbociclib for previously untreated ER+/HER2− advanced breast cancer." (PMID 36835056, 2023). "In particular, HR+ breast cancer is susceptible to CDK4/6 inhibitor therapy." (PMID 36817127, 2023). "Experience from clinical trials with cyclin D kinase 4/6 (CDK4/6) inhibitors in the setting of hormone receptor–positive (HR+)/human epidermal growth factor receptor 2-negative (HER2-) early breast cancer is provided as an illustrative example of risk stratification." (PMID 37380659, 2023).
breast cancer (continued). "In addition to the essential role of CDK4/6 in cell cycle progression through RB phosphorylation, which underlies the proliferation of HR-positive breast cancer cells, novel functions have been discovered." (PMID 36635767, 2023). "This is relevant given that breast cancer cell lines have been associated with CDK4 gene dependency, while hematologic cell lines (i.e., that may be associated with neutropenia or other cell count abnormalities) were associated with CDK6 gene dependency." (PMID 37366894, 2023). "The NATALEE study showed a significant benefit in invasive disease-free survival (iDFS) for patients with HR+/HER2- early breast cancer (eBC) at intermediate and high risk of recurrence who were treated with the CDK4/6 inhibitor Ribociclib in combination with endocrine therapy (ET)." (PMID 38003555, 2023). "Multiple studies have clarified that PI3K inhibitors are beneficial in enhancing the sensitivity of PIK3CA mutant TNBC to CDK4/6 inhibitors, and have a good effect on HR+ breast cancer carrying PIK3CA mutations, which indicates the potential of combined targeted therapy." (PMID 37719859, 2023). "Cyclin D1, frequently over-expressed in ESR1-mutated breast cancer, could activate the CDK4 and CDK6 to facilitate cell cycle progression through the G1 restriction point." (PMID 36624500, 2023). "AR’s specific role in breast cancer is currently widely unknown and its association to signaling pathways such as CDK4/6, CYP17 lyase, and PI3K can be a huge development in the treatment of TNBC." (PMID 38067367, 2023). "As single agents, CDK4/6 inhibitors that are approved for the treatment of breast cancer in combination with endocrine therapy cause G1 cell cycle arrest, whereas adenoviruses induce progression into S-phase in infected cells as an integral part of the their life cycle." (PMID 35948546, 2022). "Consistent with the findings derived from mice, in human breast cancers, loss of p18 and amplification or overexpression of cyclin D and CDK4 are frequently detected in luminal type tumors whereas loss of GATA3 expression and loss or mutation of Rb are key features of BLBCs 8, 27-31." (PMID 34976209, 2022). "RB1 loss in breast cancer is associated with resistance to many therapies, including chemotherapy and radiation, and the presence of WT RB protein is an important determinant for the efficacy of CDK4/6 inhibitor monotherapy." (PMID 34932500, 2022). "Therefore, combination analyses between Tel and the CDK4/6 inhibitors abemaciclib (Abe) and palbociclib (Palbo) were performed in a cellular model mimicking the metastatic breast cancer expressing the ERα mutated in the Y residue 537 to S (i.e., Y537S cells)." (PMID 36056637, 2022). "The inactivation of p16INK4a, a CDK inhibitor that inactivates CDK4/6 and prevents cell cycle progression at the G1/S checkpoint, resulting in the loss of cell cycle control, while dysregulation of the CDK4/6-cyclin D1 complex is a crucial stage in the genesis of breast cancer." (PMID 36406002, 2022). "The Serena-6 trial evaluates whether AZD9833 (an oral SERD) plus CDK4/6 inhibitor is superior to standard therapy in HR+/HER2− advanced breast cancer with a detectable ESR1 mutation prior to progression (NCT04964934)." (PMID 36077738, 2022). "It is still unclear whether CDK4/6i triggers a senescence-associated secretory phenotype (SASP) in breast cancer, or what the makeup of the SASP might be, and further study is needed to elucidate this." (PMID 35248122, 2022). "Results from an updated BYLieve Cohort A analysis demonstrate the ongoing benefit of alpelisib plus fulvestrant in patients with HR-positive, HER2-negative, PIK3CA-mutated advanced breast cancer whose disease progressed on or after treatment with a CDK4/6 inhibitor plus an aromatase inhibitor." (PMID 35348782, 2022).
breast cancer (continued). "CDK4/6 inhibitors in association with endocrine therapy represent the best therapeutic choice for either endocrine-sensitive or resistant hormone-receptor-positive advanced breast cancer patients." (PMID 35330128, 2022). "The addition of CDK4/6 inhibitors to NET in high-risk ER+ breast cancer may be comparable to NCT in terms of clinical value and molecular downstaging." (PMID 34064183, 2021). "However, while RB1 loss-of function mutation has been associated with adaptive resistance to CDK4/6 inhibitors in breast cancers, less is known about a potential effect of heterozygous RB1 copy number loss." (PMID 33947352, 2021). "In addition, expression profiles of CDK2 and CDK4 were associated with tumor metastasis and breast cancer subtypes, with higher expression levels in basal and Her2 subtypes than the other subtypes." (PMID 34421361, 2021). "One particular cell cycle pathway that is mutated in breast cancer involves CDK4/6." (PMID 34830174, 2021). "CDK7, a transcriptional CDK exhibiting CDK activating kinase activity on CDK2 and CDK9, has recently been found to be involved in the resistance mechanisms to CDK4/6i in CDK4/6i-resistant ER+/HER2− breast cancer cell models with loss of Rb and exhibiting cyclin E1 overexpression." (PMID 34771560, 2021). "Moreover, early adaptation of ER+ breast cancer cell models to CDK4/6i has been associated with increased activity of CDK2 by noncanonical binding with cyclin D1 mediating G1/S transition cell cycle entry." (PMID 34771560, 2021). "As a result, PDK1 is implicated in the resistance of ER+ breast cancer cells to CDK4/6 inhibitors." (PMID 34830174, 2021). "Furthermore, MMR-deficient breast cancers (specifically those with loss of MutL) have been shown to be resistant to aromatase inhibitors but sensitive to palbociclib (a CDK4/6 inhibitor)." (PMID 31522348, 2020). "Noticeably, two other classes of anti-tumor agents, i.e., CDK4/6 inhibitors and DNA-demethylating agents, cause viral-mimicry in models of mammary cancer, suggesting a potential role of the CDK and DNA-demethylation pathways in the anti-proliferative effects triggered by ATRA." (PMID 32384653, 2020). "Thus, Li and coworkers have analyzed 348 ER+ breast cancers that were treated with CDK4/6 inhibitors and identified loss-of-function mutations at the level of FAT1 and RB1 genes in association with drug resistance." (PMID 32210163, 2020). "Importantly, they also showed that the combined targeting of HER2 and CDK4/6 in lapatinib/trastuzumab-resistant HER2-positive breast cancer cells caused not only the additive but synergistic inhibition of cell growth and cell viability in vitro." (PMID 30959874, 2019). "CDK4/6 inhibitors have also been tested in PDX breast cancer models harboring ESR1 point mutations." (PMID 31106278, 2019). "Indeed, CDK4/6 inhibition was associated with a reduction in TSC2 phosphorylation in HER2-positive breast cancer mouse models and was shown to resensitize tumors to EGFR/HER2 blockade." (PMID 30167080, 2018). "p16 overexpression in Rb-deficient breast cancer cells might account for the resistance to palbociclib, as CDK4/6 enzymes might be already inhibited by the overexpressed p16." (PMID 28454587, 2017). "We hypothesize that complex alterations of the Retinoblastoma (Rb) pathway might be implicated in resistance to CDK4/6 inhibitors and aim to investigate whether signatures of Rb loss-of-function would identify breast cancer cell lines resistant to palbociclib." (PMID 27634906, 2016).
breast cancer (continued). "Whereas loss of CDK4/6 activity induced senescence in melanoma and breast cancer, it induced apoptosis in leukemia, suggesting that Notch-driven malignancies might be particularly sensitive to CDK4/6 inhibition." (PMID 26295265, 2015). "Cyclin D1 was associated with a good breast cancer prognosis but functioned independently of CDK4." (PMID 23336272, 2013). "This suggests that down-regulation of cyclin D1 and CDK4 may be associated with ST-induced G1 phase arrest in breast carcinoma cells." (PMID 24160369, 2013). "Overexpression of CDK2 and CDK4 was associated with breast cancer progression." (PMID 22616919, 2012). "Therefore, clinical studies have been conducted to investigate whether CDK4/6 inhibitors can provide clinical benefit to patients with early-stage, high-risk breast cancer through intensive adjuvant therapy." (PMID 40134916, 2025). "Moreover, loss or inactivating mutations in the FAT1 tumor suppressor gene, which normally inhibits Hippo signaling, led to the enrichment of YAP/TAZ transcription factors on the CDK6 promoter, ultimately causing CDK6 amplification and resistance to CDK4/6is in ER+ breast cancer." (PMID 40244377, 2025). "Notably, high CDK4 expression is strongly associated with poor prognosis in breast carcinoma, indicating that CDK4 may serve as a critical target in the anticancer mechanism of Simvastatin." (PMID 40864776, 2025). "Additionally, with the recent approval of Abemaciclib for the treatment of early high-risk ER+ breast cancer, sentinel node status might be valuable in identifying candidates for this CDK4/6 inhibitor." (PMID 38345718, 2024). "CDK4/6 inhibitors combined with endocrine therapy are currently the standard of care for the treatment of patients with hormone-receptor-positive (HR+)/Human Epidermal Growth Factor Receptor 2-negative (HER2−) advanced breast cancer and those with high-risk early disease." (PMID 37894292, 2023). "A recent study conducted on ERPOS advanced breast cancer patients treated with a combination of the CDK4/6 inhibitor ribociclib and letrozole showed that loss of PTEN expression due to AKT activation could lead to the development of resistance to CDK4/6 inhibition." (PMID 32605290, 2020). "Overall, this study supports the concept that breast cancer patients with MMR deficiency as assessed by immunohistochemistry may be good candidates for alternative treatment approaches such as immune checkpoint or CDK4 inhibitors." (PMID 31522348, 2020). "The success in breast cancer has also yielded great insights into the mechanisms by which tumors evade the cellular homeostasis through the genetic loss or epigenetic silencing of tumor suppressor, which encodes an endogenous inhibitor of CDK4/6 (p16INK4a) to mediate cell cycle progression." (PMID 32843618, 2020). "Cyclin-dependent kinase 4/6 (CDK4/6) inhibitors have become a major component of systemic treatment in ER+/HER2− advanced breast cancer, in which they are associated with endocrine therapy and may improve outcomes either in hormone-sensitive or insensitive disease." (PMID 31336685, 2019). "Around 30% of patients with hormone receptor-positive (HR+) breast cancer acquire resistance to endocrine therapy combined with cyclin-dependent kinase 4/6 inhibitors (CDK4/6i), which are first-line treatments in metastatic settings." (PMID 41677624, 2026). "The clinical success of cyclin-dependent kinase 4/6 (CDK4/6) inhibitors informs the feasibility of targeting cell-cycle components in breast cancer as an effective anti-tumor strategy." (PMID 41492471, 2026).